TMEM215 (transmembrane protein 215)
Tractability: Antibody: UniProt predicts a signal peptide or a membrane-spanning region.
Gene: Protein-coding gene on chromosome 9 (32,783,540 to 32,789,201, forward strand). Ensembl gene ENSG00000188133.
Subcellular location: Membrane
Subcellular location (Human Protein Atlas): Nucleoplasm; Vesicles
Gene Ontology:
Molecular function: protein binding
Biological process: negative regulation of endothelial cell apoptotic process; negative regulation of programmed necrotic cell death; sprouting angiogenesis
Cellular component: membrane
Genetic constraint (gnomAD): Loss-of-function variants: 12 observed, 14.94 expected, observed/expected ratio (o/e) 0.8, 90% interval 0.51 to 1.3. The upper end of that interval is the gene's LOEUF score, 1.3, which puts it in group 5 of 6, group 1 being the genes least tolerant of losing a copy. Missense variants: 276 observed, 313.61 expected, observed/expected ratio (o/e) 0.88, 90% interval 0.8 to 0.97. Synonymous variants: 122 observed, 132.38 expected, observed/expected ratio (o/e) 0.92, 90% interval 0.8 to 1.07.
Homologues: Orthologues: chimpanzee TMEM215 (99% identical), macaque TMEM215 (97% identical), pig TMEM215 (93% identical), dog TMEM215 (93% identical), guinea pig TMEM215 (93% identical), rabbit TMEM215 (93% identical), mouse Tmem215 (92% identical), rat Tmem215 (92% identical), tropical clawed frog tmem215 (49% identical).
Diseases named in the same sentence as TMEM215 in open-access papers:
TMEM215 is named in the same sentence as 6 diseases in open-access papers, as found by Europe PMC text mining. Sharing a sentence is not in itself a finding about the gene and the disease. The quoted sentences say what the papers report.
Azoospermia (1 paper, 2022). Absence of any measurable level of sperm,whereby spermatozoa cannot be observed even after centrifugation of the semen pellet. "For example, FAM104A was down-regulated in men with non-obstructive azoospermia (NOA), and TMEM215 was up-regulated in spermatozoa of infertile men as determined by microarray and sequencing analyses, respectively." (PMID 36211460, 2022).
deafness (1 paper, 2023). An inherited or acquired condition characterized by the complete loss of the ability to hear from one or both ears. "In addition, two LLN genes are expressed in critical loci associated with deafness, Kcnh7 in DFNA16 and Tmem215 in DFNA47." (PMID 36999169, 2023).
tumor (1 paper, 2026). "The presence of TMEM215 in endothelial cells, TMEM59 in hypoxic tumor-derived extracellular vesicles, and late B cells indicates that TMEM-directed therapies may reshape the tumor microenvironment." (PMID 41596760, 2026).
TMEM215 also shares sentences with these, for which no sentence is quoted: cancer (3 papers); endometriosis (1); infertile (1).